CTLA4 (cytotoxic T-lymphocyte associated protein 4)
Diseases named in the same sentence as CTLA4 in open-access papers (continued):
Sharing a sentence is not in itself a finding about the gene and the disease.
cancer (continued). "CTLA4 is one of the most studied immune checkpoints in malignancies, blockade of which has yielded considerable clinical benefits for patients with malignant tumors." (PMID 36812479, 2023). "In recent years, ICIs, especially those targeting CTLA-4 and PD-1/PD-1, have become the cornerstones in major cancer therapies." (PMID 37671057, 2023). "Immune checkpoint inhibitors, such as anti-PD-1 and anti-CTLA-4 inhibitors, have become the standard of care for many cancer types." (PMID 38132400, 2023). "In recent years, cancer immunotherapeutic approaches have emerged as promising strategies for cancer treatment, with PD-1 and CTLA-4 antibodies successfully used as checkpoint inhibitors to treat several types of cancer." (PMID 38140209, 2023). "Presently, different cure solutions of HCC are clinically used for advanced HCC and other cancers, and immunotherapy has more and more concentrated on PD-1 and CTLA-4 monoclonal antibodies which stop the ICI pathway." (PMID 37266152, 2023). "James P. Allison and Tasuku Honjo won the 2018 Nobel Prize in Physiology or Medicine for their successful development of inhibitors of CTLA4 and PD‐1 to treat a variety of intractable cancers." (PMID 36437106, 2023). "CTLA‐4 inhibitors, which similarly work to activate T cells to jumpstart an anti‐cancer cell immune response, have shown promise when employed in concert with cancer vaccines, chemotherapy, and radiation." (PMID 36289059, 2023). "In a recent systematic review, we provided strong evidence that malignant cells express variable levels of CTLA-4 (transcripts and functional) on the cell surface or within the cytoplasm in many types of cancer, including HNC (laryngeal and pharyngeal)." (PMID 36980582, 2023). "Immune checkpoint inhibitors (anti-PD-1/PD-L1 and anti-CTLA-4) and other anti-cancer drugs were administered to patients with RCC." (PMID 37238964, 2023). "CD80 and CD86 are ligands for CTLA4 and are expressed as markers of M2-type macrophages in various cancers." (PMID 37838657, 2023). "While monoclonal antibodies targeting CTLA4 have found applications in treating cancers like kidney and lung malignancies, the connection between Triple-Negative Breast Cancer Stem Cells (TN-BCSCs) and CTLA4 remains inadequately elucidated." (PMID 37838657, 2023). "Equally important though, is the reliable measurement of CTLA-4 levels which would allow for a detailed quantitative pharmacological and toxicological assessment of the target in cancer immunotherapies." (PMID 37110545, 2023). "Antibodies targeting inhibitory pathways, including CTLA-4 and PD-1, have paved the way for a new generation of cancer therapeutics." (PMID 37143732, 2023). "PD-1 and CTLA-4 are the prototype ICs and the most extensively utilized therapeutic targets in cancer immunotherapy." (PMID 37342323, 2023). "ICIs such antibodies targeting programmed cell death 1 (PD-1), cytotoxic T lymphocyte-associated protein 4 (CTLA-4) and PD1 ligand 1 (PD-L1) have showed promising therapeutic effect and have been applied for many cancer types in the clinic." (PMID 36892953, 2023). "Studies in solid tumor models provided some evidence of using propranolol as a chemo‐ or radio‐sensitizer, or to improve the outcome of cancer immunotherapies (e.g. anti‐CTLA4 therapy)." (PMID 36245401, 2023). "Monoclonal antibodies widely used in immune control, such as PD-1, PD-L1, and cytotoxic T lymphocyte antigen 4 (CTLA-4), have significantly improved the prognosis of patients with advanced cancer." (PMID 36798137, 2023). "Antibodies targeting cytotoxic T-lymphocyte antigen 4 (CTLA4) or PD-1–PD-L1 have been approved for use in various cancers." (PMID 38003338, 2023). "Based on our analysis of immune checkpoints, the high- and low-risk groups showed a significant difference, and we focused on CTLA4 and PD-1 (targets for cancer immunotherapy)." (PMID 37614950, 2023).
cancer (continued). "Immunotherapies including CTLA-4/PD-L1 inhibitors present a wide developmental foreground in cancer therapy." (PMID 36707884, 2023). "A significant development in the field of cancer immunotherapy is the discovery ofproteins like programmed cell death protein 1 (PD1), programmed cell death ligand 1 (PDL–1), and cytotoxic T lymphocyte-associated antigen 4 (CTLA4)." (PMID 37056346, 2023). "Both CTLA-4 and PD-1 are common inhibitory checkpoints on activated T cells and have been found to be the most reliable targets for cancer treatment." (PMID 37577750, 2023). "By interacting with programmed cell death 1/ligand 1(PD-1/PD-L1) and cytotoxic T lymphocyte-associated antigen 4 (CTLA-4), ICIs prevent cancers from escaping from antitumor immune response, leading to significant improvement in clinical outcome." (PMID 37124234, 2023). "The prognostic value of immune-related genes (PD-1, PD-L1, CTLA-4, etc.)in cancers has been well-established." (PMID 36672292, 2023). "first adopted the low-dose ICI rationale for stage IV cancer patients, by combining an off label low-dose of anti-CTLA-4 plus anti-PD-1 antibody blockade with hyperthermia and individualized dosing of IL-2 treatment." (PMID 37860001, 2023). "Current immunotherapies directed against the inhibitory receptors, such as programmed cell death protein 1 (PD-1) and cytotoxic T-lymphocyte-associated protein 4 (CTLA-4), have shown efficacy in various types of cancers that were previously untreatable." (PMID 38022598, 2023). "Despite the beneficial effects of radiotherapy and some immunogenic drugs, the exposure of Tregs, DCs, TAMs, and also cancer cells to some DAMPs such as adenosine lead to overexpression of some co-inhibitory molecules such as Tim-3, CTLA4, TIGIT, and PD-L1." (PMID 37221555, 2023). "Cancer cells express CTLA4 too and this mechanism corresponds with immune tolerance and causes cancer progression." (PMID 37605149, 2023). "We analyzed another pan‐cancer cohort (N = 570), which we obtained from cBioportal, to validate our finding that high TIM‐3 is associated with high CTLA‐4 and PD‐1." (PMID 38132831, 2023). "These monoclonal antibodies reactivate T-cell response against cancer cells, by blocking either the lymphocyte inhibitory receptor CTLA4 or the interaction between T-cell receptor PD-1 with its ligands PDL-1 and PDL-2 at the surface of cancer cells." (PMID 37435488, 2023). "Exhausted T cells in cancer express high levels of inhibitory receptors, including PD-1, CTLA-4, TIM-3, LAG3, BTLA, and TIGIT, most of which are also known as Treg markers." (PMID 36901957, 2023). "In recent years, cancer immunotherapy represented by anti-PD-1/PD-L1, anti-CTLA4, and CAR-T has made considerable progress." (PMID 37240834, 2023). "In the early stages of carcinogenesis, CTLA-4 can reduce T-cell activation and allow cancer proliferation." (PMID 38067379, 2023). "Immune checkpoint inhibitors (ICIs), such as CTLA-4, PD-1, and PD-L1 inhibitors, are a revolutionary cancer immunotherapy that improves treating a wide range of cancers." (PMID 37568794, 2023). "Therapies that target T cell inhibitory checkpoint proteins like CTLA4 and programmed cell death-Ligand 1 (PD-L1) have shown efficacy for various cancers, including HNSCCs." (PMID 37798374, 2023). "Checkpoint inhibition (CPI) has become a major research focus for cancer immunotherapy since the discovery of PD-1, PD-L1 and CTLA-4." (PMID 37046612, 2023). "Combining personalized cancer vaccines with PD-1, PD-L1, and CTLA4 inhibitors is now being used in different clinical trials to treat various cancer types." (PMID 38041084, 2023). "Although the immune checkpoint inhibitors of PD‐1/PD‐L1 and CTLA‐4 appear to be promising therapeutic approaches against various advanced cancers, it appears to be partially effective as only a subset of patients respond to this treatment." (PMID 37936711, 2023).
cancer (continued). "ICIs, including PD-1, PD-L1, and CTLA-4 inhibitors, provide treatment options for patients with malignant tumor." (PMID 37759294, 2023). "It should be noted that, recently, cancer therapy has made a quantum leap using immunological methods, such as anti-CTLA4 12 and anti-PD-1/PD-L1 monoclonal antibodies that inactivate negative regulators or checkpoints of the adaptive immune system." (PMID 38136555, 2023). "At present, immunotherapy targeting immune checkpoints, especially programmed cell death protein 1/programmed cell death ligand 1 (PD-1/PD-L1) and CTLA-4 blockers have become feasible in the treatment of many malignant tumors." (PMID 36891150, 2023). "Some of the most studied and better characterized, due to their importance in cancer immunity and immunotherapy, have been CTLA-4 (lymphocyte cytotoxic antigen-4) and PD-1 (programmed cell death-1)." (PMID 36672279, 2023). "The immune checkpoint receptor ligands to PD1 and CTLA-4 are up-regulated in cancer cells as part of dodging the immune system, thus silencing the T-cell activation." (PMID 37765192, 2023). "Cancer patients with severe immune-related adverse events (irAE) after receiving anti-CTLA-4/PD-1 combination immunotherapy also have markedly reduced peripheral B cells." (PMID 36909522, 2023). "Anti-CTLA-4 resistance is affected by the expression of IFNG1, whereas anti-PD-1 resistance is affected by the expression of IFNG2." (PMID 36909185, 2023). "Over the last few decades, immunotherapy has revolutionized cancer therapy, such as anti-CTLA4, anti-PD1, and anti-PDL1." (PMID 37165046, 2023). "CTLA-4 negatively regulates immune function through its interaction with B7 (CD80/CD86) expressed on the surface of cancer cells, and its competitive action with CD28, which activates T cells." (PMID 37790929, 2023). "The application of dual combinations is encouraged by the evidence that combination anti-CTLA-4 plus anti-PD-1 checkpoint blockade has shown enhanced efficacy compared to monotherapy in a wide range of cancer types." (PMID 37251920, 2023). "For instance, ICOS has positive relationships with PDCD1, TIGIT, CD274, and CTLA4 in the majority of cancer types, indicating a broad co-expression landscape." (PMID 36855091, 2023). "In cancer patients responding to anti-PD-1 or anti-PD-1/CTLA4, clonally expanded T cells showed elevated TRM and cytotoxicity programs, suggesting rapid response capability of TRM in response to ICI." (PMID 36798126, 2023). "The landscape of current cancer immunotherapy is dominated by antibodies targeting PD-1/PD-L1 and CTLA-4 that have transformed cancer therapy, yet their efficacy is limited by primary and acquired resistance." (PMID 37332070, 2023). "ICIs aim to increase the activity of the immune system against cancer by breaking tolerance mediated by CTLA-4 and PD-1 in the TME." (PMID 37342323, 2023). "Cancer cells induce immunosuppressive cells, such as Tregs expressing CTLA4, and suppress the action of dendritic cells via the CTLA4 pathway." (PMID 37996567, 2023). "To date, clinically approved ICIs targeting PD-1/PD-L1 and CTLA-4 have shown promising efficacy and became the standard treatments for various cancers, such as advanced melanoma, NSCLC, and solid tumors with microsatellite instability." (PMID 36845142, 2023). "The cytotoxic T-lymphocyte-associated antigen 4 (CTLA-4) and lymphocyte activation gene-3 (LAG-3) are similar kind of checkpoint proteins on immune cells which are used by cancer cells to bind and evade the immune cell signalling-mediated death." (PMID 38112935, 2023). "To facilitate the economical production of ICI, we produced an anti-CTLA-4 antibody in N. benthamiana plants for effective cancer immunotherapy." (PMID 37711295, 2023). "Due to adverse side effects and limited observation, other CTLA-4 blockades that have shown good anti-cancer effects in many trials, such as tremelimumab and nivolumab, have not received FDA approval." (PMID 37576404, 2023).
cancer (continued). "In this review, we reviewed 71 patients with cancer (40 male and 31 female) treated with anti-PD-1/PD-L1 and anti-CTLA-4 inhibitors." (PMID 37305530, 2023). "In numerous clinical trials on various cancers, the CTLA-4 antibody ipilimumab has been combined with an anti-PD-1 antibody to demonstrate greater efficacy than single-agent treatment." (PMID 36587630, 2023). "Ipilimumab (anti-CTLA-4 antibody) has shown promising results in treating melanoma, but progress has been slow in other cancer types because of low response rate and immunotherapy-related adverse events." (PMID 37794509, 2023). "In the cancer microenvironment, including GC, immune checkpoint molecules such as CTLA-4 and PD-L1 are overexpressed and broadly induce the evasive mechanism." (PMID 37577519, 2023). "Despite somewhat different phenotypes, both CTLA‐4 and PD‐1 pathways have been targeted in cancer immunotherapy with remarkable efficacy against a range of tumours." (PMID 36727298, 2023). "Anti-ICOS agonists were already tested in mice studies and in clinical trials for cancer immunotherapy, and show promising results when used in combination with other checkpoint inhibitors like anti-PD-1 and anti-CTLA-4 antibodies." (PMID 37056774, 2023). "Immune checkpoint inhibitors (ICIs) by targeting PD-1/PD-L1 or CTLA-4 have markedly improved the outcome of cancer patients." (PMID 36865537, 2023). "Currently, Atezolizumab (antibody to PD-L1) and Ipilimumab (antibody to CTLA-4) were approved for cancer treatment." (PMID 36917087, 2023). "The interaction of the immune check inhibitors (ICI) with the PD-1, PD-L1, and CTLA-4 in the tissues leads to a disruption of the host T-cell signaling and the upregulation of the T-cell immune response against cancer cells." (PMID 37835475, 2023). "After decades of research on immune checkpoints inhibitors (ICIs), the use of immunotherapies targeting programmed death-1 (PD-1), its ligand PD-L1 and cytotoxic T lymphocyte antigen 4 (CTLA4) have been reported to be effective in many cancer types." (PMID 37142983, 2023). "Immunotherapies targeting immune checkpoint receptors or ligands such as Cytotoxic T-Lymphocyte-Associated protein-4 (CTLA-4), Programmed Death -1 (PD-1) and its ligand (PD-L1), are currently being widely exploited in clinical trials for multiple cancer types." (PMID 36672355, 2023). "Studies have demonstrated that compared with monotherapy, combination therapy with PD1 and CTLA4 inhibitors results in better survival improvement in several cancers." (PMID 36993976, 2023). "Specifically, they identified immune checkpoints (CTLA-4 and PD-1) and demonstrated the feasibility of anti-cancer immunotherapy involving antibodies targeting these checkpoints." (PMID 37205993, 2023). "Abatacept being a CTLA-4 agonist induces T cell anergy leading to suppression of inflammation, however, risks include infections and possible progression of cancer." (PMID 38045806, 2023). "TMB, MSI, and PD-L1 expression have been approved by the FDA for predicting the efficacy of ICIs in cancer patients, while PD-1, CTLA-4 expression and glycolysis score have been reported as potential biomarkers for predicting response to ICIs therapy." (PMID 37296415, 2023). "In recent years, some immunotherapy, such as the programmed cell death protein 1(PD-1), cytotoxic T lymphocyte-associated protein 4 (CTLA-4), and the chimeric antigen receptors T cells (CAR-T), have achieved promising clinical therapeutic effects in cancer." (PMID 36976060, 2023). "Checkpoint inhibitors are used as methods of immunotherapy, using monoclonal antibodies directed at CTLA4 and PD-1, proteins receptors that are located on the cell membrane of T cells and cancer cells." (PMID 37631922, 2023). "For CRC, ICBs such as anti-PD-L1, anti-PD-1 or anti-CTLA-4, are only indicated for the treatment of dMMR cancer." (PMID 38035338, 2023).
cancer (continued). "For example, the benefits of therapy were observed in cancer patients treated with anti-PD-L1, anti-PD-1, and/or anti-CTLA-4 blockade therapies." (PMID 37367867, 2023). "Monoclonal antibody-based drugs targeting CTLA4 have been identified as a therapeutic approach to enhance the immune system’s anti-cancer activity." (PMID 38112634, 2023). "Immune checkpoint inhibitors, targeting CTLA-4 and the programmed cell death protein-1 (PD-1)/programmed cell death ligand-1 (PD-L1) pathways have shown remarkable potential in malignant tumors." (PMID 37198621, 2023). "Effective immune-checkpoint inhibitors that target CTLA-4 or the PD-1–PD-L1 axis, have been approved as targets for cancer treatment." (PMID 37214432, 2023). "However, in the cancer microenvironment, cancer cells use immune checkpoints to escape antitumor immune responses, involving pathways mediated by immune checkpoint molecules such as programmed death protein-1 (PD-1), cytotoxic T-lymphocyte-associated protein 4 (CTLA-4), and various other factors." (PMID 37790929, 2023). "Immune checkpoint inhibitors, including those that target the programmed cell death 1 and programmed cell death ligand 1 (PD-1 and PD-L1) and cytotoxic T lymphocyte antigen 4 (CTLA-4) pathways, are revolutionizing cancer therapy." (PMID 37400985, 2023). "As a conclusion, the current findings provided a mechanistic platform for the development of acquired radioresistance in EMT6RR_MJI through overexpression of CTLA-4 and PD-1, and novel knowledge on therapeutic targets for recurrent radioresistant cancers." (PMID 36813833, 2023). "These co-inhibition molecules are called “immune checkpoint proteins,” and inhibition of these protein pathways (immune-checkpoint inhibition) by blocking CTLA-4 and PD-L1 with mAbs, etc., have shown potential advances in cancer immunotherapy." (PMID 36810079, 2023). "Several inhibitory immunoreceptors have been discovered and studied in cancers, and apart from PD-1 also include CTLA-4, LAG3, TIM3, TIGIT, BTLA, etc." (PMID 38067344, 2023). "IPS has been established to be a better predictor of immunotherapy response in cancer patients undergoing anti-PD-1 and anti-CTLA-4 treatment." (PMID 36911676, 2023). "On the other hand, the regulation of co-inhibitory molecules such as PD-L1, Tim-3, TIGIT, and CTLA4 by cancer cells, Tregs, TAMs, DCs, and MDSCs can exhaust the anticancer potency of cytotoxic CD8 + T lymphocytes." (PMID 37221555, 2023). "With the discovery of immune checkpoint proteins (e.g., CTLA-4 and PD-1) as key factors in mediating immunologic escape for many cancers, there was renewed interest in studying immune checkpoint blockade in MPM." (PMID 37296902, 2023). "Nowadays, immunotherapy is a main option for cancer therapy, particularly immune checkpoint blockade (ICB) targeting cytotoxic T-lymphocyte-associated antigen 4 (CTLA-4) and PD-1." (PMID 37723519, 2023). "BsAbs that target CTLA-4 are a novel class of immunotherapies that are being developed to improve the effectiveness and safety of immune checkpoint blockade in cancer treatment." (PMID 37441075, 2023). "Subsequently, the correlation between key pan-carcinoma molecules (including CTLA4, PDCD1LG2, IDO1, and HAVCR2) and CD86 was calculated." (PMID 37064861, 2023). "Vogelstein and colleagues' research suggest that cancer mismatch repair errors can selectively up-regulate immunosuppression checkpoints such PD-1/PD-L1, CTLA-4, and IDO, resulting in local immunosuppression and TNA aggregation." (PMID 35401745, 2022). "Immune checkpoint inhibitors therapy is a kind of immunotherapy that work by blocking the binding of checkpoint proteins (PD-1, PD-L and CTLA-4) with partner proteins so that T-cell became free and active to attack cancer cells." (PMID 35756634, 2022). "Immune checkpoint inhibitors represented by antibodies against PD-1, PD-L1, and CTLA-4 constitute the current frontier in cancer therapy." (PMID 35178154, 2022).